ACOX1 (acyl-CoA oxidase 1)
Diseases named in the same sentence as ACOX1 in open-access papers (continued):
Sharing a sentence is not in itself a finding about the gene and the disease.
metabolic disorders (8 papers, 2021 to 2025). "Both interventions share ACOX1 inhibition mechanisms, but the purified extract achieved comparable efficacy via a much smaller dose, underscoring the extract's translational value in treating ACOX1-associated metabolic disorders." (PMID 40686867, 2025). "Inhibition of ACOX1 caused multiple metabolic disorders by improving the metabolism of the reactive oxygen species (ROS) and mitochondrial lipid." (PMID 38213102, 2024). "We therefore propose luteolin-4’-O-glucoside as a candidate ACOX1 inhibitor and therapeutic agent for metabolic disorders, enabling exploration of flavonoid-based therapies." (PMID 40686867, 2025). "Their identification as ACOX1 inhibitors elucidates their mechanism in suppressing peroxisomal fatty acid β-oxidation, providing valuable insights for metabolic disease therapeutics." (PMID 40686867, 2025). "Inhibition of ACOX1 activity by herbal formula or chemical molecules has been shown to reduce hepatic lipid accumulation, improve insulin sensitivity, and alleviate oxidative stress, making it a promising strategy for treating metabolic diseases." (PMID 40686867, 2025).
neurodegenerative disease (2 papers, 2020 to 2024). A disorder of the central nervous system characterized by gradual and progressive loss of neural tissue and neurologic function.
retinopathy (2 papers, 2020 to 2021). "Furthermore, it is highly likely that a disturbed retinal PUFA homeostasis strongly contributes to the retinopathy observed in ZSD and peroxisomal β-oxidation (e.g., ACOX1 and MFP2) deficiency patients." (PMID 33921065, 2021).
ACOX1 also shares sentences with these, for which no sentence is quoted: adrenoleukodystrophy (2 papers); myopathy (2); ovarian carcinoma (2); Zellweger spectrum disorders (2); acute kidney injury (1); Aicardi-Goutières syndrome (1); alopecia areata (1); Alzheimer disease (1); anemia (1); arterial disease (1); atopic dermatitis (1); benign tumors (1); Blindness (1); bone metastasis (1); brain glioma (1); breast tumor (1); cardiomyopathy (1); cerebellar ataxia (1); Cerebellar atrophy (1); clear cell renal cell carcinoma (1); cognitive deficits (1); colitis (1); colon adenocarcinoma (1); COVID-19 (1); cyst (1); cystic kidneys (1); deafness (1); developmental delay (1); endometriosis (1); esophageal cancer (1).
A further 28 diseases each share a sentence with ACOX1 in 1 paper.